STAT3 (signal transducer and activator of transcription 3)
Diseases named in the same sentence as STAT3 in open-access papers (continued):
Sharing a sentence is not in itself a finding about the gene and the disease.
cancer (continued). "STAT family comprises seven proteins, among which STAT3 has been shown to be overexpressed in many types of cancer, especially breast cancer." (PMID 36536188, 2022). "Once the STAT3 signaling cascade has been activated, it can affect multiple aspects of cancer progression." (PMID 35800364, 2022). "While cytosolic STAT3 is an obvious choice as a therapeutic target, it was shown that the dysfunction of mitochondrial STAT3 can create sufficient stress for the cancer cells to induce apoptosis." (PMID 36429126, 2022). "In fact, CUR has been reported to suppress the proliferation, migration, and invasion of cancer cells by suppressing STAT3 activity." (PMID 36003508, 2022). "This chemokine was combined with CR2 and activated the JAK/STAT3 pathway, which awakened the dormant cancer cells and promoted cancer progression clinically." (PMID 35634311, 2022). "STAT3 mainly possesses a tumor-promoting role in cancer, and its downregulation is beneficial for cancer treatment." (PMID 35317831, 2022). "Nowadays, drug resistance to cancer therapies is a major problem in combating this disease, and various studies affirm that feedback activation of STAT-3 is majorly responsible for mediating drug resistance." (PMID 36014565, 2022). "In vitro, hesperidin affected PD-L1 expression in HN6 cells and HN15 cells by reducing the phosphorylation of STAT1 and STAT3, thereby inhibiting cancer cell survival and avoiding evasion of antitumor immunity." (PMID 36080397, 2022). "Cancer-derived extracellular vesicles increase M2 polarization by activating signaling pathways such as STAT3, p38MAPK, NF-κB, ERK1/2, and PI3K/AKT and reprogram M1 tending cells into the cancer-promoting M2 end of the macrophage phenotype spectrum." (PMID 36612080, 2022). "STAT3 activation by IL-6 has been shown to regulate MSC-induced chemoresistance, and the blockage of STAT3 activation (with AG490, a JAK2 inhibitor) improved the susceptibility of cancer cells to chemotherapeutic agents." (PMID 35954425, 2022). "The efficacy of SDL-1 as a STAT3 degrader for the treatment of other human cancers or conditions in which STAT3 plays an important role warrants further investigation." (PMID 36034876, 2022). "Sirtuin 1, known as NAD-dependent deacetylase sirtuin-1, promoted cancer cell proliferation and metastasis via STAT3/MMP-13 signaling, which is also found participated in the abnormal metabolism pathways in AML." (PMID 36727051, 2022). "In this study, we found that GRd protects against aging‐ and cancer‐induced skeletal muscle wasting by binding to STAT3, enhancing muscle function, and suppressing the expression of protein degradation factors such as MSTN, atrogin‐1, and MuRF‐1." (PMID 36127129, 2022). "The Janus kinase 2/signal transducer and activator of transcription 3 (JAK2/STAT3) pathway plays an important role in regulating cancer stem-cell properties of ATCs." (PMID 36430869, 2022). "It is a promising inhibitor of STAT3 and represses cancer angiogenesis via blocking the action of STAT3 and the expression of VEGF and HIF-1α." (PMID 35355732, 2022). "Signal transducer and activator of transcription 3 (STAT3) plays a carcinogenic role in a variety of malignant tumours and is positively correlated with poor prognosis." (PMID 35665592, 2022). "Such a strategy offers a potent, reversible, and efficacious approach to degrade STAT3 proteins for malignant epithelial-derived cancer treatment." (PMID 36509291, 2022). "Activated STAT3 induces cancer transformation by affecting cellular pathways related to cell growth, apoptosis, and tumorigenesis." (PMID 36299882, 2022).
cancer (continued). "Given the activity of ROS against STAT3 and the strong scientific rationale for STAT3 being a critical driver for cancer stemness and immune evasion, an investigation of BBI608 in combination with immune checkpoint inhibitors was imperative." (PMID 35267638, 2022). "These exosomes mediate immune evasion of cancer cells via induction of PD-L1 expression and transfer of STAT3." (PMID 35765040, 2022). "Since cucurbitacin treatments decrease the level of phosphorylated JAK or STAT3 and its downstream targets, such as Bcl-2, in cancer cells, the ability to stimulate apoptosis in cells has also been described." (PMID 36355498, 2022). "The mechanism of NEN in cancer mainly involves the uncoupling of oxidative phosphorylation, as well as the regulation of Wnt/β-catenin, mTORC1, STAT3, NF-κB, and Notch signaling pathways, which is the same as NIC." (PMID 36555754, 2022). "Elevated STAT3 levels found across several human cancers and the constitutive STAT3 activity promote cell proliferation, invasion and evasion from cell death." (PMID 35159046, 2022). "Gingerol modulates several cancer-related pathways, including NF-κB, STAT3, and activator protein-1 (AP-1)." (PMID 36421353, 2022). "Later, IL-32β has been found to play an antitumor activity role as it downregulates vital cancer progression proteins including antiapoptotic proteins, proliferation, and cell growth regulatory proteins through the same pathways, NF-κB and STAT3." (PMID 35281008, 2022). "Among the major immunosuppressive cells in the TIME, MDSCs are able to activate the NF-κB, STAT3, and promote cancer development." (PMID 36313280, 2022). "In a cancer setting, the IL-6R mAb Tocilizumab inhibits the phosphorylation of STAT3 in osteosarcoma cell lines, leading to the attenuation of pro-growth signaling and resultant reduction in cell proliferation." (PMID 35053592, 2022). "To investigate the potential mechanism underlying palbociclib-induced apoptosis in LUSC cells, we examined the STAT3 signaling, which was constitutively activated in LUSC progression and closely associated with apoptosis in various cancers." (PMID 36005200, 2022). "STAT3 overexpression is also one of the mechanisms known to correlate with cancer cells’ radio-resistance." (PMID 35625738, 2022). "Newer compounds are being synthesized and evaluated by computational methods to improve the understanding of the STAT3 functional mechanism and aid in the design of STAT3 inhibitors as anti-cancer drugs." (PMID 35844493, 2022). "Cytokine IL-6 is the main inflammatory mediator and stimulator of STAT3, which can block programmed cell death and facilitate cancer survival." (PMID 36371217, 2022). "Inhibition of STAT3 activation is known to be the critical molecular event of resveratrol-suppressed cancer cells." (PMID 36430869, 2022). "The JAK2-modulated STAT3 transcription factors are involved in many processes, such as immune response, inflammation, and cancer progression, by activating proinflammatory cytokines, growth factors, and oncogenes." (PMID 35111269, 2022). "Particularly, IL-6 can promote metastasis by aberrantly activating the STAT3 pathway, supporting cancer stem cells (CSC)." (PMID 35269666, 2022). "Many TRIM proteins have been reported to activate the STAT3 pathway, thereby promoting cancer progression." (PMID 36288633, 2022). "The JAK2/STAT3 signaling pathways also play a critical role in the growth, proliferation, and metastasis of cancers." (PMID 35111269, 2022). "DJ-1 has been reported negative regulator of PTEN (Phosphatase And Tensin Homolog) via reducing expression of PTEN and plays a central regulator of astrogliosis in brain injury via activation of STAT3, which also plays a critical role in cancer pathogenesis." (PMID 36202793, 2022). "Consistently, the integrin-Src-Stat3 pathway has been reported to be involved in maintaining stemness and promoting the proliferation of cancer stem cells in various tumors 60-66." (PMID 35673564, 2022).
cancer (continued). "Currently, there are 18 clinical trials testing STAT3 inhibitors as cancer treatments listed in the database (clinicaltrials.gov), with 8 of these trials now completed, three recruiting, and one not yet recruiting." (PMID 36221123, 2022). "TQ has been shown to inhibit cancer cell proliferation; arrest cancer cell cycle progression; and, induce pro-apoptotic effects with the targets of Bcl-2, caspases, PPArs, NF-kB, STAT3, MAPK, Akt and ROS16." (PMID 35246558, 2022). "Particular attention has been drawn to not only to STAT3 hyperactivity in cancer, but the increased abundance of its activating cytokines, the IL-6 superfamily of cytokines." (PMID 35053592, 2022). "An increasing number of studies have provided strong evidence that AKR1C1 is a key component in the STAT3 pathway, which is critical for metastasis in different cancer models." (PMID 35370661, 2022). "STAT3 is an important transcription factor and is well known for its roles in cancer proliferation, survival, invasion, and immunosuppression is also implicated in mesenchymal GBM." (PMID 35574370, 2022). "Activation of STAT3 contributes to the development of many cancers, while the inhibition of STAT3 reportedly elicits apoptotic cell death and stimulates immune-related activities to eliminate cancer cells." (PMID 35884919, 2022). "Activation of IL-6/JAK2/STAT3 pathway is closely associated with EMT and stem cell-like features, ultimately leading to poor prognosis in patients with various cancers." (PMID 36591515, 2022). "Given that STAT3 is a potential target for cancer therapy, there are numerous direct and indirect STAT3 inhibitors." (PMID 35401187, 2022). "The overexpression of STAT3 itself a prognostic factor in several cancers including pancreatic ductal adenocarcinoma (PDAC)." (PMID 35269689, 2022). "Taken together, STAT3 signaling pathways play a key role in cancer metastasis and are found to be regulated by IL-32." (PMID 35281008, 2022). "Altogether, these results imply the potential of PMEO to suppress cancer metastasis by impairing STAT3 signaling." (PMID 35956786, 2022). "Pectolinarigenin suppresses cancer cell proliferation, induces apoptosis, reduces the level of STAT3, inhibits migration and invasion, and preserves the epithelial–mesenchymal transition (EMT)." (PMID 35327559, 2022). "Therapeutic agents targeting the STAT3 pathway have been well studied as treatment modalities for cancers." (PMID 35158821, 2022). "SHP-1-mediated STAT3-inhibition and subsequent apoptosis induction is an appealing anti-cancer strategy that has been reviewed." (PMID 35941532, 2022). "Consistently, several previous articles have reported anticancer activities for CPT, as a specific natural STAT3 inhibitor, as well as naringenin, a well-known natural flavonoid, against different types of cancers." (PMID 35606804, 2022). "STAT3 signaling is a significant pathway for cancer inflammation as it is aberrantly activated in most cancers of epithelial origin." (PMID 35563421, 2022). "A recent study reports that STAT3 acts as a positive transcription factor to induce the expression of the main parts of proteasome subunits in cancer cells." (PMID 35269802, 2022). "To study the molecular mechanism by which Pdia4 regulated Stat3 and the Vegf family in cancer stroma, we first examined the relationship between Stat3 and Pdia4." (PMID 35170261, 2022). "This study revealed the important functions of the RNF7-JAK/STAT3 pathway in modulating apoptosis and glycolysis, which are utilized by cancer cells to escape multiple levels of stress imposed by the immune system and various drugs." (PMID 35562668, 2022). "Among them, STAT3 is a transcription factor that has been profoundly studied in cancer and inflammation." (PMID 36591515, 2022). "STAT3 has been shown to play an important role in cancer progression and typically acts as an oncogene." (PMID 35314590, 2022).
cancer (continued). "The importance of STAT3 in the maintenance of a wide variety of cancer stem cells is well documented." (PMID 34482626, 2022). "It has the promising inhibitors of STAT3 and represses cancer angiogenesis via blocking the action of STAT3 and the expression of VEGF and HIF-1α." (PMID 35359383, 2022). "In cancer, TAMs were reported to secrete IL-6 via STAT3 pathway leading to expansion of cancer stem cells and breast cancer progression." (PMID 36325334, 2022). "This proto-oncogene is also overexpressed when not mutated or translocated, being upregulated downstream of oncogenic pathways such as STAT3 or Wnt/B-catenin, which are known to be activated in cancers including PEL and MM." (PMID 35453482, 2022). "The site-specificity of Stat3 phosphorylation should be taken into account in clinical trials that aim to disrupt Stat3 signaling in breast and other cancers." (PMID 36017196, 2022). "On the whole, STAT3 hyperactivation in KM-LUAD cancer cells confers survival advantages and initiates a cascade of autocrine and paracrine signaling that alters the TME." (PMID 35406557, 2022). "A dysfunctional JAK2/STAT3 signaling pathway can induce cancer and inhibit apoptosis, promote cancer cell migration by regulating E-cadherin and vimentin expression, and promote EMT." (PMID 36158694, 2022). "Regulators of STAT3 modulate host immunity to cancer through direct inhibition of STAT3 expression/inhibition of the STAT3 upstream pathway." (PMID 36313702, 2022). "Several signaling pathways are aberrantly hyperactivated in diverse cancers, among which activation of transcription factor STAT3 accounts for immunosuppression." (PMID 36755812, 2022). "Immune escape and immunosuppression are among the features in TME; STAT3 in cancer cells can inhibit the activation of dendritic cells and promote enhanced metabolism of substances in the TME." (PMID 36291659, 2022). "A similar phenomenon was observed in cancer cells, where increased mito STAT3 was found to be required for glutathione synthesis." (PMID 36699722, 2022). "Collectively, these results indicate that JAK2-mediated phosphorylation of STIP-1 is critical for sustaining the JAK2/STAT3 signaling pathway in cancer cells." (PMID 35269562, 2022). "It has also been reported to inhibit STAT3 signaling by the suppression of STAT3 activation and enhanced STAT3 protein degradation in various cancer cells." (PMID 36358791, 2022). "Nevertheless, higher expression of IL-32α has been found to activate NF-κB and STAT3 pathways and induce the production of IL-6, thus supporting the cancer proliferation and progression in MM patients." (PMID 35281008, 2022). "STAT3 activation promotes cancer cell growth and metastasis and also induces chemoresistance in many cancers." (PMID 35369571, 2022). "STAT3 activation also regulates the expression of different cancer cells; namely CD 44, and CD 133 positive cells which maintain the stem cell-like characteristics in HCC cells by inducing the Notch signaling pathway." (PMID 36374927, 2022). "Trienomycin A blocks the phosphorylation of STAT3, thus inhibiting the STAT3 pathway and exerting its anti-cancer therapy in vitro and in vivo." (PMID 35401187, 2022). "The result of several canonical pathways includes molecular mechanisms of cancer, role of tissue factor in cancer, STAT3 pathway, PI3K/AKT signaling, and so on, which are vital for the progression of cancers." (PMID 35433477, 2022). "The activation of signal transducer and activator of transcription 3 (STAT3) has been reported in several types of cancer, where it acts as an oncogene." (PMID 35314590, 2022). "Cytokine activation of STAT3 is considered the principal pathway in the activation of cancer, and IL-6 is considered an upstream activator of JAK2/STAT3." (PMID 36313702, 2022).
cancer (continued). "KM-LUAD models are vital to understanding the mechanisms of STAT3 and to appraise therapies that block the IL-6/STAT3 signaling pathway across the variety of cancer and immune cells within the TME." (PMID 35406557, 2022). "STAT3 is reported to be constitutively active in several cancers, which leads to malignant transformation by playing a critical role in stimulating cell proliferation and arresting apoptosis." (PMID 35778602, 2022). "An understanding of specific downstream targets of STAT3 will enable an elucidation of the specific mechanisms that action STAT3 has in cancer progression." (PMID 35053592, 2022). "Acquiring the traits of cancer stem cells (CSCs) by TrkC/DJ-1/STAT3 signaling pathway leads to the induction of chemoresistance via upregulation of ABC transporters and anti-apoptotic genes." (PMID 36202793, 2022). "Phosphorylated EGFR also activates the JAK2/STAT3 signalling axis to upregulate the transcription of a variety of proteins involved in the survival of cancer cells." (PMID 35158954, 2022). "After targeting three important modules responsible for paclitaxel drug resistance in cancer i.e., STAT3, FUT4, and P-GP, we were interested to determine the role of MALAT1 in this scenario." (PMID 35281907, 2022). "Specifically, Stat3—which in its own right confers many of the cell-intrinsic hallmarks of cancer—regulates miRNA expression, including miR-21 expression in cultured cells." (PMID 35053428, 2022). "The JAK/STAT3 pathway is the main signal transduction pathway of IL-22, and the activation of STAT3 promotes the invasion ability of malignant tumors." (PMID 35669104, 2022). "STAT3 is tightly related with malignant tumors, and constitutive activation of STAT3 exerts a critical action in cell survival, angiogenesis, immune escape and inflammation." (PMID 36506558, 2022). "Another sorafenib analogue, SC-43, was reported to block STAT3 signaling to increase the sensitivity of cancer cells to chemotherapeutic drugs like docetaxel." (PMID 35414025, 2022). "Constitutive activation of STAT3 has been detected in several cancer stem cells, including prostate, breast, and GBM, where it promotes a stem-cell phenotype and survival." (PMID 35954407, 2022). "The S1PR1 antagonist FTY720 can significantly inhibit EMT program by inactivating STAT3 signaling, further modulating the resistance of cancer cells to therapy." (PMID 35251963, 2022). "For superficial STAT3-dependent cancers such as HNSCC, intratumoral injection is expected to enhance the efficacy of PROTACs, as well as overcome the potential risk to normal tissues or organs." (PMID 36509291, 2022). "The STAT3 protein is continuously activated in tumor cells, making it an effective target for cancer prevention." (PMID 36547471, 2022). "The interplay between IL-8 and Stat3, and E-cadherin and Stat3 has been described in other types of cancer, but the potential interaction linking these molecular pathways has not been interrogated in the context of ETBF-mediated colorectal tumourigenesis." (PMID 35468857, 2022). "STAT3 is an important regulator of stem cell self-renewal and cancer cell survival in the animal model of PDAC." (PMID 35565185, 2022). "Surprisingly, all forms of STAT3 were lower expressed in the cancer cores than in the benign cores, and the lowest expression was detected in the tissues with higher GS." (PMID 36230984, 2022). "Here, we found that PIKE-A promoted SDHA expression via increasing FTO expression through activation of STAT3 signaling and maintaining mitochondrial membrane potential, leading to promoting cancer cell proliferation." (PMID 36232604, 2022). "The role of the JAK/STAT3 signaling pathway in the regulation of metastasis, the transition of cancer stem cells, and chemoresistance of cancer by EMT has sparked the development of therapeutic targets." (PMID 35819532, 2022). "Recently, some studies have also indicated that STAT3 participates in the process of autophagy during cancer." (PMID 35847939, 2022).